YES1 (YES proto-oncogene 1, Src family tyrosine kinase)
Diseases named in the same sentence as YES1 in open-access papers (continued):
Sharing a sentence is not in itself a finding about the gene and the disease.
ovarian carcinoma (7 papers, 2017 to 2024). A malignant neoplasm originating from the surface ovarian epithelium. "Our findings provide insight into the miR-133a/YES1/autophagy axis as a novel diagnostic biomarker and potential gene therapeutic target for ovarian cancer chemotherapy." (PMID 35012539, 2022). "YES1 is overexpressed in tumor samples obtained from patients with breast and ovarian cancer, as well as in recurrent or resistant cases of ovarian cancer." (PMID 38338729, 2024). "Knockdown of YES1 led to the suppression of proliferation and cell cycle arrest in ovarian cancer cells." (PMID 35012539, 2022). "A clinical retrospective study showed that overexpression of Yes1 indicated favourable prognosis and increased platinum sensitivity in primary epithelial ovarian cancer patients." (PMID 35012539, 2022). "The results indicated that the autophagy signalling pathway was markedly enhanced in ovarian cancer patients with high YES1 expression." (PMID 35012539, 2022). "In this study, we analysed the Cancer Genome Atlas (TCGA) ovarian cancer cohort to identify the YES1 signature as the top 500 YES1-correlated genes (Pearson correlation P value <0.05)." (PMID 35012539, 2022). "Our results also demonstrate that YES1 knockdown suppresses cisplatin resistance in ovarian cancer in vitro and that YES1 overexpression induces cisplatin resistance both in vitro and in vivo." (PMID 35012539, 2022). "Bioinformatics analysis revealed that YES1 expression was upregulated in recurrent cisplatin-resistant ovarian cancer tissue, and in vitro experiments also verified its upregulation in cisplatin-resistant cell lines." (PMID 35012539, 2022). "Taken together, our findings suggest that miR-133a targets the 3′UTR of YES1 and reversely regulates the expression of YES1, which ultimately regulates cell autophagy in ovarian cancer with cisplatin resistance." (PMID 35012539, 2022). "Taken together, these findings suggested that miR-133a targets YES1 and downregulates its expression, thereby reducing cisplatin resistance in ovarian cancer cells." (PMID 35012539, 2022). "Yes1 knockdown significantly suppressed the cisplatin resistance of ovarian cancer cells by inhibiting autophagy in vitro." (PMID 35012539, 2022). "In this study, we further investigated the roles of YES1, a protein highly expressed in cisplatin-resistant tissue and cell lines, in cisplatin-resistant ovarian cancer." (PMID 35012539, 2022). "To further understand how YES1 plays a role in cisplatin resistance in ovarian cancer, we first demonstrated that YES1 was significantly highly expressed in both A2780-DDP and SKOV3-DDP cells by RT–qPCR and WB, which is consistent with the results of bioinformatics analysis." (PMID 35012539, 2022). "Our results suggest that the miR-133a/YES1 axis plays a critical role in cisplatin resistance in human ovarian cancer by regulating cell autophagy, which might serve as a promising therapeutic target for ovarian cancer chemotherapy treatment in the future." (PMID 35012539, 2022). "Furthermore, we demonstrated that YES1 affects cisplatin resistance by regulating autophagy in both ovarian cancer cells and a xenograft model." (PMID 35012539, 2022). "Taken together, our research suggested that miR-133a directly targets YES1 by binding its 3′UTR area and that the miR-133a/YES1 axis might regulate cisplatin sensitivity via autophagy in ovarian cancer." (PMID 35012539, 2022). "Among the 50 drugs screened by the community, 13 drugs were used as therapy for ovarian cancer and all of the drug could target to the YES1 or TYMS." (PMID 31068972, 2019). "Moreover, rapamycin, an autophagic agonist, reversed siYes1-induced cisplatin resistance, and chloroquine, an autophagy antagonist, reversed Yes1-OE-induced cisplatin resistance, which further demonstrated that YES1 affects cisplatin resistance in ovarian cancer by regulating cell autophagy." (PMID 35012539, 2022).
ovarian carcinoma (continued). "Moreover, we studied whether YES1 regulates cisplatin resistance in ovarian cancer." (PMID 35012539, 2022). "We also observe co-clustering of ovarian cancer cell lines OVCAR5, IGROV1, and OVCAR4, which had high predicted recruitment of YES1." (PMID 30653502, 2019). "Furthermore, we identified miR-133a as a potential YES1 posttranscriptional regulator that directly binds the 3′UTR of YES1 and downregulates its expression in ovarian cancer." (PMID 35012539, 2022). "However, how YES1 regulates chemoresistance in recurrent ovarian cancer is not fully understood." (PMID 35012539, 2022).
colorectal cancer (5 papers, 2017 to 2026). A primary or metastatic malignant neoplasm that affects the colon or rectum. "Here we report that the pro-survival form of Fas not only crosstalks with the EGFR but also significantly intensifies EGFR signaling in anti-EGFR-resistant colorectal cancer cells via the Yes-1/STAT3-mediated pathway." (PMID 30127519, 2018). "Using an evolution-guided pY291-Fas proxy, RNA interference, and site-specific phospho-protein detection, we show that pY291-Fas significantly intensifies EGFR signaling in anti-EGFR-resistant colorectal cancer cells via the Yes-1/STAT3-mediated pathway." (PMID 30127519, 2018).
non-small cell lung carcinoma (5 papers, 2021 to 2023). A group of at least three distinct histological types of lung cancer, including non-small cell squamous cell carcinoma, adenocarcinoma, and large cell carcinoma. "Among members of the Src family, YES1 expression showed the highest association with poor outcomes in patients with non-small cell lung cancer." (PMID 34884609, 2021). "Previous research has reported that miR-133a inhibits cell proliferation in non-small-cell lung cancer by targeting YES1." (PMID 35012539, 2022). "YES1 has been previously identified as a biomarker for non-small cell lung cancer and esophageal adenocarcinoma and may be a potential membrane biomarker." (PMID 36873459, 2022).
melanoma (4 papers, 2015 to 2024). A malignant, usually aggressive tumor composed of atypical, neoplastic melanocytes. "ERK activation is driven by YES1, suggesting a potential mechanism that contributes to drug resistance in patients with melanoma and BRAF mutations who undergo combined BRAF and MEK inhibition." (PMID 38338729, 2024). "The expansion of the CD24-positive subpopulation leads to an elevated YES1 phosphorylation and enhanced expression of Wnt target genes, subsequently promoting melanoma formation and metastasis compared to isogenic CD24-negative cells." (PMID 38338729, 2024). "The expression and kinase activity of YES1 were consistently higher in 20 human melanoma cell lines than that of melanocyte cell lines." (PMID 38338729, 2024). "Cells with a high propensity for brain metastasis in melanoma show intrinsically elevated YES1 activity compared to their parent or less metastatic counterparts." (PMID 38338729, 2024). "The cordycepin treatment downregulated the expression of ZEB1, HMGA2 and TWIST1 by more than 50% but had minimal effects on ADAM9, RAC1, SALL4, CTNNB1, ZEB2 and YES1 in these two melanoma cell lines." (PMID 25868853, 2015). "YES1 is more important than Src in melanoma progression and metastasis." (PMID 38338729, 2024). "In addition, in melanoma A375 cells, YES1 overexpression triggered MEK-independent ERK activation." (PMID 38338729, 2024).
rhabdomyosarcoma (4 papers, 2017 to 2023). A rare aggressive malignant mesenchymal neoplasm arising from skeletal muscle. "YES1 amplification and overexpression are found in a variety of tumors, and siRNA- or shRNA-mediated YES1 downregulation can inhibit the proliferation and growth of rhabdomyosarcoma, NSCLC, and pancreatic cancer cell lines." (PMID 36909198, 2023). "The major role of YES1 in tumor progression is supported by the decreased YES1 expression correlated with the impaired growth abilities of several malignancies, including malignant mesothelioma, rhabdomyosarcoma, and pancreatic cancer." (PMID 28818100, 2017).
glioma (3 papers, 2019 to 2024). A benign or malignant brain and spinal cord tumor that arises from glial cells (astrocytes, oligodendrocytes, ependymal cells). "Fyn, Yes1, and Src were consistently expressed in both glioma stem cells and primary glioma cells among SFKs, whereas LCK was exclusively expressed in primary glioma cells." (PMID 38338729, 2024). "In yet another in vitro and in vivo study, hsa_circ_0046701 (circ-YES1) was significantly up-regulated in glioma, and circ-YES1 knockdown was found to inhibit cell invasion and proliferation." (PMID 37009887, 2023).
triple-negative breast carcinoma (3 papers, 2018 to 2025). An invasive breast carcinoma which is negative for expression of estrogen receptor (ER), progesterone receptor (PR), and human epidermal growth factor receptor 2 (HER2). "Combining YES1 inhibitors with taxanes has been shown to improve treatment efficacy by inducing maladaptive chromosomal instability, thereby reducing the survival of triple-negative breast cancer cells." (PMID 40362400, 2025). "Moreover, downregulation of YES1 via miR-133 was demonstrated to inhibit cancer cell proliferation triple-negative breast cancer cell lines." (PMID 36386788, 2022). "Previous work has suggested that through the Src-family kinase, Yes-1, EGFR amplifies FasL-induced cell migration in triple-negative breast cancer cells." (PMID 30127519, 2018).
bladder cancer (2 papers, 2022 to 2025). "Studies have shown that YES1 gene amplification exists in many cancers such as oesophagal, lung, bladder cancer, etc.; this indicates kinase YES1 is an appealing target in anticancer therapy." (PMID 35630545, 2022). "Moreover, METTL1-mediated m7G-3′-tiRNA LysTTT promoted bladder cancer malignancy by binding to ANXA2 to enhance its phosphorylation by Yes1." (PMID 40045194, 2025).
COVID-19 (2 papers, 2021 to 2023). A disease caused by infection with severe acute respiratory syndrome coronavirus 2. "The results indicated six hub DEGs for comparison of T1DM and COVID-19 convalescence (CD3G, YES1, ALAS2, MYO1C, NCR3, PRKACB) and two hub DEGs for comparison of T2DM and COVID-19 convalescence (PTRF, EHD1)." (PMID 38169604, 2023). "We analyzed the relationship of immune cell infiltration with two hub DEGs (CD3G and YES1) in the T1DM and COVID-19 convalescence data, and with two other hub DEGs (PTRF and EHD1) in the T2DM and COVID-19 convalescence data." (PMID 38169604, 2023). "Forkhead-box C1 (FOXC1) is a TF that regulates the expression of CD3G and YES1, and may therefore affect the development of T1DM after COVID-19 convalescence." (PMID 38169604, 2023).
lung adenocarcinoma (2 papers, 2020 to 2026). A carcinoma that arises from the lung and is characterized by the presence of malignant glandular epithelial cells. "YES1 amplification has been found in 15% of lung adenocarcinoma and 25% of lung squamous cell carcinoma patients, and YES1 expression was reported to be related to a shorter OS in NSCLC patients." (PMID 32744377, 2020).
malignant mesothelioma (2 papers, 2017 to 2024). A malignant neoplasm of the pleura or peritoneum, arising from mesothelial cells. "A phosphotyrosine proteomic analysis indicated the activation of SFKs such as Src, Fyn, and YES1 in malignant mesothelioma." (PMID 38338729, 2024). "Among these SFKs, only the inhibition of YES1 resulted in the suppression of cell growth in malignant mesothelioma cells." (PMID 38338729, 2024).
prostate carcinoma (2 papers, 2019 to 2021). A carcinoma that arises from epithelial cells of the prostate gland. "Circ_0057553/miR-515-5p signaling modulates glycolysis, invasion, migration, apoptosis, and proliferation of prostate cancer cells by regulating YES1." (PMID 34774083, 2021). "For instance, the downregulation of miR-199a contributes to paclitaxel (PTX) resistance through targeting the oncogene Yamaguchi sarcoma viral homolog 1 (YES1) in prostate cancer." (PMID 31754335, 2019).
skin cancer (2 papers, 2024 to 2025). "Other reports have verified that YES1 is expressed at higher levels in squamous cell carcinoma than in other skin cancer types." (PMID 38338729, 2024). "Among SFKs, YES1 is frequently amplified and overexpressed in a variety of human tumors, including lung, breast, ovarian, and skin cancers." (PMID 38338729, 2024). "YES1 is an SFK and is frequently amplified and overexpressed in various human malignancies, including lung, breast, ovarian, and skin cancers, and has been increasingly recognized for its role in promoting cell proliferation, survival, invasiveness, and chemoresistance." (PMID 40362400, 2025).
thyroid cancer (2 papers, 2018 to 2021). "It has been reported that lncRNA-H19 functions as a ceRNA by acting as a sink for miR-17-5p in the modulation of YES1 expression to prompt thyroid cancer cell proliferation and migration." (PMID 29673400, 2018). "miR-17-5p targeting YES1 induced thyroid cancer progression." (PMID 34130587, 2021).
Alzheimer disease (1 paper, 2018). A progressive, neurodegenerative disease characterized by loss of function and death of nerve cells in several areas of the brain leading to loss of cognitive function such as memory and language. "Moreover, analysis of the GSE48350 dataset confirmed similar changes in HDAC1, CDC42 and YES1 expression in Alzheimer's disease, thereby providing a molecular connection between aging and Alzheimer's disease (AD)." (PMID 30341976, 2018).
autoimmune disease (1 paper, 2025). A disorder resulting from loss of function or tissue destruction of an organ or multiple organs, arising from humoral or cellular immune responses of the individual to their own tissue constituents. "STX8 and YES1 are implicated in T-cell activation, MAP4K5, RRM2B, FOXO1, ERBB2IP and INPPL1 can promote inflammation and KIM1, MVK and BANK1 have been associated with autoimmune diseases." (PMID 40247373, 2025).
chronic myeloid leukemia (1 paper, 2025). "In this study, we applied two SFK-targeted inhibitors: dasatinib, approved by the FDA for chronic myeloid leukemia 36, and NXP900, a novel SRC/YES1-inhibitor currently undergoing clinical trial (NCT05873686)." (PMID 39776795, 2025).
colonic adenomas (1 paper, 2010). "YES1 encodes a SRC-family kinase and its tyrosine kinase activity has been shown to be elevated in colonic adenomas compared to its activity in adjacent normal mucosa." (PMID 20698951, 2010).
colorectal adenoma (1 paper, 2015). An adenoma that arises from the colon or rectum. "Most interestingly, in the Gaspar Colon colorectal adenoma dataset Bcl6 expression was significantly positively correlated with MAPK9, MAP2K4 and Yes1, and negatively with Dlg2, relative to normal intestinal mucosa." (PMID 26187947, 2015).
epilepsy (1 paper, 2017). A brain disorder characterized by episodes of abnormally increased neuronal discharge resulting in transient episodes of sensory or motor neurological dysfunction, or psychic dysfunction. "The remaining two genes SGK1 and YES1 have also been suggested to contribute to the progression of epilepsy." (PMID 28255556, 2017).
lymphoma (1 paper, 2022). A malignant (clonal) proliferation of B- lymphocytes or T- lymphocytes which involves the lymph nodes, bone marrow and/or extranodal sites. "Our random forest biomarker discovery pinpointed three novel biomarker genes not previously associated with BCNHL, YES1, FERMT2, and FAM98B, which show high fidelity in predicting lymphoma presence based on transcriptional levels in B-cells." (PMID 36873459, 2022).
ovarian tumour (1 paper, 2022). "Xenograft tumour implantation further demonstrated that Yes1 overexpression promoted ovarian tumour development and cisplatin resistance." (PMID 35012539, 2022). "Yes1 overexpression significantly enhanced ovarian tumour growth and induced cisplatin resistance, with a slower tumour growth curve and slower tumour growth volume after cisplatin injection intraperitoneally in the YES1-NC group than in the YES1-OE group." (PMID 35012539, 2022).
peritonitis (1 paper, 2025). Inflammation of the peritoneum (tissue that lines the abdominal wall and covers most of the organs in the abdomen). "Conversely, Forkhead Box Protein O1 (FOXO1), Lipoprotein Lipase (LPL), and Tyrosine-protein Kinase Yes (YES1) were downregulated in peritonitis-afflicted animals when compared to the sham group." (PMID 40102905, 2025).
Pleural effusion (1 paper, 2022). The presence of an excessive amount of fluid in the pleural cavity. "An in-depth allele-specific copy number analysis of the pleural effusion sample revealed a complex genomic landscape and highlights a strong copy-aberrant loss of heterozygosity of YES1 gene and a MYC allele-specific gain." (PMID 35199053, 2022). "Gains for YES1, encoding a SFK, and MYC genes were observed both in the pericardial biopsy and the pleural effusion samples." (PMID 35199053, 2022). "In our case, immunocytochemical characterization of pleural effusion revealed EMT features, confirmed also in primary cell line, highlighting the potential putative role of YES1 in inducing EMT." (PMID 35199053, 2022).